RNF135 (ring finger protein 135)
Diseases named in the same sentence as RNF135 in open-access papers (continued):
Sharing a sentence is not in itself a finding about the gene and the disease.
Osteochondroma (1 paper, 2024). A common, benign cartiliginous neoplasm arising from the metaphysis of bone. "In this study, we detected drastically higher RNF135 expression in human OS tissues than human osteochondroma tissues." (PMID 39118262, 2024). "In both OS and osteochondroma specimens, RNF135 protein was localized to the cytoplasm and cell membrane." (PMID 39118262, 2024). "Semiquantitative immunoreactivity evaluation showed that 90% of the cell population in OS tissues were RNF135 positive while only 15% were positive in osteochondroma tissues (p < 0.001)." (PMID 39118262, 2024). "RNF135 expression in 20 human OS and 20 human osteochondroma specimens were evaluated by means of immunohistochemistry staining." (PMID 39118262, 2024). "We detected significantly higher RNF135 levels in human OS tissues than human osteochondroma tissues." (PMID 39118262, 2024). "We detected RNF135 expression in 90% of the cell population in OS specimens, but only 15% of the cell population in osteochondroma specimens stained positive for RNF135, showing drastic RNF135 upregulation in human OS." (PMID 39118262, 2024). "IHC and H&E staining of human OS and osteochondroma tissues revealed that RNF135 was mainly localized in the cell membrane and cytoplasm, with OS tissues showing markedly higher staining signal than osteochondroma tissues." (PMID 39118262, 2024). "In this study, we evaluated RNF135 expression in 20 human OS and 20 human osteochondroma specimens by means of IHC staining." (PMID 39118262, 2024). "IHC staining for RNF135 in human osteochondroma and OS tissues." (PMID 39118262, 2024).
osteosarcoma (1 paper, 2024). A usually aggressive malignant bone-forming mesenchymal neoplasm, predominantly affecting adolescents and young adults. "However, whether RNF135 plays a role in the development of human osteosarcoma (OS) remains unknown." (PMID 39118262, 2024).
pancreatic cancer (1 paper, 2022). "RNF135 may be intimately associated with the development and progression of pancreatic cancer." (PMID 36495591, 2022). "Using RNA-seq data from 33 different kinds of TCGA malignancies, an investigation was conducted on the mRNA expression of RNF135 in pancreatic cancer patients." (PMID 36495591, 2022).
RASopathies (1 paper, 2024). "Of interest, some RASopathies may also have common pathways with interferonopathies, such as the overgrowth–macrocephaly–facial dysmorphism syndrome, associated with RNF135 mutations encoding Riplet, a co-receptor of the pattern recognition receptor RIG-I." (PMID 38791606, 2024).
tumor (11 papers, 2016 to 2025). "The aberrant expression of RNF135 is associated with immune cell infiltration, the expression of immunological checkpoints, and tumor heterogeneity in pan-cancer." (PMID 36495591, 2022). "RNF135 is aberrantly elevated in several tumor tissues, and its aberrant expression is associated with the prognosis of malignancies." (PMID 36495591, 2022). "There was a strong correlation between the levels of the RNF135 genetic mutation and some tumor progression." (PMID 36495591, 2022). "This suggests that RNF135 is intimately associated with the tumor heterogeneity of BRCA and has significant implications for BRCA." (PMID 36495591, 2022). "In addition, a strong correlation was seen between RNF135 expression and immune cell infiltration, tumor mutation burden, microsatellite instability, and immunoregulators." (PMID 36495591, 2022). "Our results confirm Wang’s findings that RNF135 is downregulated in HCC, where it acts as a tumor suppressor and is linked to a poor prognosis." (PMID 39766812, 2024). "This study investigated expression profiles, prognostic relevance, genetic modification, immune cell infiltration, and tumor heterogeneity of RNF135 in pan-cancer." (PMID 36495591, 2022). "With the aid of The Cancer Genome Atlas and Gene Expression Omnibus, we have fully mapped the expression profiles, prognostic relevance, genetic modification, immune cell infiltration, and tumor heterogeneity of RNF135 in 33 malignant tumors." (PMID 36495591, 2022). "Our results demonstrated the significance of RNF135 in tumor immunology, metabolic activity, and epithelial-to-mesenchymal transition, as well as a mechanism by which it influences these processes." (PMID 36495591, 2022). "To characterize the function of RNF135 as a tumor suppressor in HCC, we performed GSEA analysis using the TCGA data." (PMID 35145901, 2021). "Since RNF135 was positively correlated with all six types of immune cells, it is undeniable that RNF135 is related to anti-tumor immunity." (PMID 35145901, 2021). "Using univariate Cox regression analysis, RNF135 methylation (HR = 1.960; 95% confidence interval (CI): 1.367–2.810; P <0.001), tumor stage (HR = 2.375; 95% CI: 1.646–3.426; P <0.001) were associated with increased risk of HCC death." (PMID 35145901, 2021). "RNF135 might be utilized as a biomarker to anticipate how a tumor will behave and may have a significant role in how TNBC cells grow and migrate, according to the findings of this study." (PMID 36495591, 2022). "Future research on RNF135 expression and the immunological environment of the tumor may aid in the development of immunotherapy-based cancer therapeutics." (PMID 36495591, 2022). "RNF135 functions as a tumor suppressor and is involved in tumor immune microenvironment in HCC." (PMID 35145901, 2021). "The negative correlation between RNF135 expression and tumor mutational burden (TMB) reinforced our suspicion (r = −0.2411, p <0.001)." (PMID 35145901, 2021). "Moreover, the results of immunohistochemistry staining implied that the expression of RNF135 in the shRNF135-xenografted tumours was reduced compared with the normal expression of RNF135 in shPLV-Ctr-xenografted tumours." (PMID 26856755, 2016). "Therefore, the current literature suggests that RNF135 may exhibit oncogenic or antitumor effects, depending on the specific type of tumor involved." (PMID 39118262, 2024). "Interestingly, RNF135 is a regulator of several tumor suppressor genes." (PMID 37145209, 2023). "In addition, other immune system pathways, such as interferon gamma signaling and regulation of cytokine production was also found, suggesting that RNF135 may have potential effects on anti-tumor immune and immune therapy." (PMID 35145901, 2021). "In conclusion, RNF135 may act as a tumor suppressor, regulating HCC cell migration." (PMID 35145901, 2021).
tumor (continued). "In TCGA database analysis, both NF1 and RNF135 showed higher expression levels in the LUAD tumor samples than in the normal samples (P = 1.2E−10 for NF1 and P = 8.8E−04 for RNF135, Mann–Whitney U test)." (PMID 36702236, 2023). "In conclusion, we demonstrated that RNF135 was epigenetically silenced in HCC and served as a tumor suppressor in HCC development." (PMID 35145901, 2021). "RNF135 expression was significantly downregulated and hyper-methylated in HCC tissues compared with adjacent non-tumor tissues." (PMID 35145901, 2021). "Thus, RNF135’s effect on tumour progression and malignancy may be via the Erk pathway." (PMID 26856755, 2016). "RNF135-positive TAMs demonstrated significantly improved intercellular communication with aggressive tumor subtypes in comparison to RNF135-negative TAMs." (PMID 41097797, 2025). "Immunohistochemistry showed RNF135 expression and six immune cell types (B cell, CD8+ T cell, CD4+ T cell, macrophage, neutrophil, and dendritic cell) were high in normal HCC tissues and the expression were low in tumor tissues." (PMID 35145901, 2021). "RNF135 expression correlated with tumor purity but not TIICs." (PMID 36495591, 2022). "Haploinsufficiency of certain genes may contribute to dysmorphic facial features, overgrowth and reduced cognitive capability (RNF135) or heart defects (ADAP2), whereas others might have tumor suppressive function, thus their deletion promote tumor development (SUZ12, ATAD5)." (PMID 34168676, 2021).
cancer (9 papers, 2017 to 2024). A tumor composed of atypical neoplastic, often pleomorphic cells that invade other tissues. "Since its identification in 2009, RNF135 has been linked to many human cancers." (PMID 39118262, 2024). "In a pan‐cancer analysis, RNF135 was found to be dysregulated in many human cancers, and its expression level correlated with disease progression and prognosis." (PMID 39118262, 2024). "RNF135 was expressed inconsistently in various cancers, and variations in RNF135 expression predicted survival outcomes for cancer patients." (PMID 36495591, 2022). "A Spearman relationship was performed between RNF135 single nucleotide variants (SNV) and mRNA in pan-cancer." (PMID 36495591, 2022). "Our understanding of RNF135’s role in cancer was greatly aided by bioinformatics, and molecular biology confirmed that it promoted cancer in TNBC." (PMID 36495591, 2022). "We found a substantial link between RNF135 gene expression and immune infiltration in 34 different cancer species by using the coefficient to build the highly related immune infiltration score." (PMID 36495591, 2022). "Our data demonstrated a favorable correlation between RNF135 and the majority of immunomodulators in pan-cancer." (PMID 36495591, 2022). "Ring finger protein 135 (RNF135) is an E3 ubiquitin ligase with RING finger domains that plays a crucial role in the development of several forms of cancer." (PMID 36495591, 2022). "Furthermore, we discovered that low RNF135 expression was associated with poorer overall survival (OS) (P = 1.3e-08) and disease-free survival (DFS) (P = 8.5e-14) in the total cancer population." (PMID 36495591, 2022). "In addition, we started observing the expression of RNF135 in various clinical phases of pan-cancer." (PMID 36495591, 2022). "Pan-cancer investigations aimed at elucidating the immunological function of RNF135 are essential for identifying the sorts of malignancies that may respond favorably to anti-RNF135 immunotherapy." (PMID 36495591, 2022). "Moreover, RNF135 methylation (P = 0.001), family history of cancer (P = 0.038), and HBV/HCV infection (P = 0.003) were found to be related to death." (PMID 35145901, 2021). "Additionally, the link between RNF135 and cancer has been shown." (PMID 36495591, 2022). "Another important finding is the significant downregulation of RNF135 in HCC compared to CCA, CRLM and PCLM, suggesting that its lower expression is characteristic of HCC and may help to differentiate HCC from other cancers." (PMID 39766812, 2024). "In addition, significantly higher expression of HOXC4 was detected in CCA, significantly lower expression of RNF135 in HCC and significantly lower expression of OSMR in CRLM compared to the other cancers." (PMID 39766812, 2024). "Neither the expression profile of RNF135 nor its importance in the diagnosis of pan-cancer have been elucidated as of yet." (PMID 36495591, 2022).
infection (4 papers, 2009 to 2023). The state of being infected such as from the introduction of a foreign agent such as serum, vaccine, antigenic substance or organism. "RIG-I is stabilized by ubiquitinylation by RNF135/RIPLET in mammals to increase type I interferon signaling during infection." (PMID 37622121, 2023). "Correlation analysis between RNF135 methylation status and clinical characteristics in HCC from the TCGA revealed that RNF135 methylation status was significantly related to HBV/HCV infection (P = 0.011) and recurrence/progression (P = 0.018)." (PMID 35145901, 2021). "Here we see that RNF135 is upregulated by infection with either BC500 or VN1203 in all tissues, while TRIM25 is upregulated in both lung and spleen during VN1203 infection." (PMID 34804075, 2021).
genetic diseases (1 paper, 2016). "The gene RNF135, which has been identified by the genome project previously, was found to be a cause of human genetic diseases such as neurofibromatosis." (PMID 26856755, 2016).
RNF135 also shares sentences with these, for which no sentence is quoted: developmental delay (2 papers); liver cancer (2); anaplastic astrocytoma (1); avian influenza (1); cardiovascular diseases (1); cholangiocarcinoma (1); Cognitive impairment (1); esophageal carcinoma (1); HIV-1 infection (1); intellectual disabilities (1); lung adenocarcinoma (1); lymphoblastic leukemia (1); Macrocephaly (1); metastatic cancers (1); oligodendroglioma (1); pancreatic ductal adenocarcinoma (1); prostate carcinoma (1); schizophrenia (1); Sotos syndrome (1).